HLF (HLF transcription factor, PAR bZIP family member)
Synonyms: MGC33822
Tractability: PROTAC: ubiquitination databases record sites on it.
Gene: Protein-coding gene on chromosome 17 (55,264,960 to 55,325,187, forward strand). Ensembl gene ENSG00000108924.
Subcellular location: Nucleus
Subcellular location (Human Protein Atlas): Nucleoplasm
Gene Ontology:
Molecular function: DNA-binding transcription activator activity, RNA polymerase II-specific; protein binding; protein heterodimerization activity; sequence-specific DNA binding; sequence-specific double-stranded DNA binding; DNA-binding transcription factor activity, RNA polymerase II-specific; double-stranded DNA binding; RNA polymerase II cis-regulatory region sequence-specific DNA binding; DNA-binding transcription factor activity
Biological process: positive regulation of transcription by RNA polymerase II; regulation of transcription by RNA polymerase II; regulation of DNA-templated transcription
Cellular component: nucleoplasm; nucleus; RNA polymerase II transcription regulator complex; chromatin
Genetic constraint (gnomAD): Loss-of-function variants: 3 observed, 18.11 expected, observed/expected ratio (o/e) 0.17, 90% interval 0.074 to 0.43. The upper end of that interval is the gene's LOEUF score, 0.43, which puts it in group 1 of 6, group 1 being the genes least tolerant of losing a copy. Missense variants: 290 observed, 388.27 expected, observed/expected ratio (o/e) 0.75, 90% interval 0.68 to 0.82. Synonymous variants: 144 observed, 154.35 expected, observed/expected ratio (o/e) 0.93, 90% interval 0.81 to 1.07.
Homologues: Orthologues: chimpanzee HLF (100% identical), macaque HLF (100% identical), dog HLF (99% identical), pig HLF (99% identical), guinea pig HLF (99% identical), mouse Hlf (98% identical), rat Hlf (97% identical), tropical clawed frog hlf (84% identical), zebrafish hlfa (73% identical), zebrafish hlfb (72% identical), rabbit HLF (66% identical), Drosophila melanogaster Pdp1 (44% identical), and 3 more. Paralogues in human: TEF (51% identical), DBP (45% identical).
Diseases named in the same sentence as HLF in open-access papers:
HLF is named in the same sentence as 79 diseases in open-access papers, as found by Europe PMC text mining. Sharing a sentence is not in itself a finding about the gene and the disease. The quoted sentences say what the papers report.
leukemia (21 papers, 2007 to 2026). A malignant (clonal) hematologic disorder, involving hematopoietic stem cells and characterized by the presence of primitive or atypical myeloid or lymphoid cells in the bone marrow and the blood. "HLF fusion proteins that resulted from chromosomal translocation (e.g., E2A-HLF) are often linked to leukemia." (PMID 27561985, 2016). "HLF has been previously implicated in leukemia as a fusion with E2A in B-precursor ALL as well as direct target of Meis1 in Hox-mediated transformation." (PMID 26986211, 2016). "Notably, we also established a B-ALL cell line from the GR-BALL-3 sample, validated at the phenotypic and genomic levels, in which expression of the TCF3::HLF fusion transcript associated with aggressive leukemia has been confirmed." (PMID 37723198, 2023). "HLF is a proto-oncogene whose expression product is a subset of the bZIP transcription factors and can cause abnormal transcriptional regulations of target genes which is related to leukemia development." (PMID 28673327, 2017). "HLF, a transcriptional factor, plays an significant regulatory function in various tumors, particularly leukemia and participates in therapy-mediated immunogenic cell death." (PMID 36155774, 2022). "Hepatic leukemia factor (HLF) is a critical transcription factor that plays an important regulatory role in many cancers, especially leukemia and may be involved in therapeutically induced immunogenic cell death." (PMID 31998783, 2020). "Finally, rs12067906 (p-value = 9.584×10-6) also maps in a DNAse hypersensitive region and onto two TFBS (corresponding to Gfi1 and HLF, both related to leukemia and several related pathologies)." (PMID 24289864, 2013). "Notably, TCF3::HLF directly regulates MEF2C expression through its enhancer, as interference disrupted MEF2C transcription and inhibited leukemia propagation." (PMID 42090509, 2026). "3.1.d—Mutation in NPM1, FLT3 and DNMT3A AML with three-way interaction among NPM1, DNMT3A and FLT3 occurs in around 6% of AML and is characterized by high leukemia stem cell (LSC) frequency, aberrant immunophenotype (with low CD34 and high CD56) and overexpression of hepatic leukemia factor (HLF)." (PMID 36831522, 2023). "Freshly purified human blood monocytes were primed for 24 h with either LF-IC (M860+LF), or hLF, or M860, or complex between chicken ovalbumin (OVA) and OVA-specific mouse mAb M562 (OVA-IC), followed by evaluation for ability to kill leukemia line cells of Jurkat and Raji in vitro." (PMID 31600968, 2019). "Human monocytes primed with LF-IC, but not hLF or M860 alone, or control ICs, showed strong tumoricidal activity on leukemia cell lines Jurkat and Raji through induction of secreted Granzyme B (GzB)." (PMID 31600968, 2019).
acute lymphoblastic leukemia (15 papers, 2007 to 2026). Leukemia with an acute onset, characterized by the presence of lymphoblasts in the bone marrow and the peripheral blood. "Hepatic leukemia factor (HLF), a member of the proline and acidic amino acid–rich basic leucine zipper family of transcription factors, was first identified in acute lymphoblastic leukemia in the form of e2A-HLF fusion gene." (PMID 40779629, 2025). "HLF (originally known as E2A-HLF) in childhood acute lymphocytic leukemia is a chimeric transcription factor produced by the translocation of E2A on chromosome 19 and HLF on chromosome 1737." (PMID 36566289, 2022). "The HLF gene has been found in translocations together with E2A in human acute lymphoblastic leukemia and enforced HLF expression has been reported to enhance both HSC engraftment and to inhibit apoptosis." (PMID 17712416, 2007). "HLF, which is high-expressed in liver tissues but low-expressed lung tissues, is initially identified as a protein related to TCF3 driving acute lymphoblastic leukemia, but it is also demonstrated to be robustly hypermethylated in NSCLC when compared to normal tissues." (PMID 33612479, 2021).
lung carcinoma (8 papers, 2019 to 2025). "Hepatic leukemia factor (HLF) is thought to be closely associated with lung cancer metastasis." (PMID 40124619, 2025). "To determine if HLF suppresses lung metastasis in other types of cancer, we evaluated multiple cancer cell lines from cancers typically associated with lung metastasis in patients, including osteosarcoma, colorectal cancer, lung cancer and melanoma." (PMID 40473600, 2025). "Our research has identified HLF as a suppressor of metastasis, not only in renal cancer but also in other cancer types including osteosarcoma, melanoma, colorectal cancer and lung cancer." (PMID 40473600, 2025). "Hepatic leukemia factor (HLF) is thought to be closely associated with tumor metastasis, and our previous study demonstrated that HLF was down-regulated in lung cancer tissues and negatively correlated with the number of metastatically active CTCs in the peripheral blood of patients." (PMID 40124619, 2025). "Interestingly, in the lung cancer cell line H1299, HLF overexpression affected both primary tumor growth and lung metastasis." (PMID 40473600, 2025). "In addition, Wang and colleagues found that the expression of the HLF gene was much reduced in lung cancer tissues when compared to normal samples." (PMID 38711550, 2024). "The analysis of the nodes with iRegulon showed HLF, a TF with the ability to regulate four nodes, has an enrichment score of 6000, has six possible binding motifs, and is negatively regulated in eight sets of lung cancer data." (PMID 36101460, 2022). "HLF has previously been reported to be methylated in lung cancer." (PMID 30867848, 2019). "Various molecular pathways and genes such as BMAL1, SIRT1, HLF, and PER1 and their implications in aging, circadian rhythms, and lung cancer will also be discussed." (PMID 39812541, 2025). "Further multivariate Cox regression analyses displayed that SATB2, HLF, and NPAS2 were independently predictive of lung cancer prognosis." (PMID 34925645, 2021). "In accordance with the regression coefficient derived from multivariate Cox regression models and expression value of SATB2, HLF, and NPAS2, a TF genomic model was conducted for lung cancer prognosis." (PMID 34925645, 2021). "Collectively, our findings proposed and verified a 3-TF genomic model (SATB2, HLF, and NPAS2) for prediction of lung cancer outcomes." (PMID 34925645, 2021). "Some genes with hypermethylated promoters have been reported in lung cancer, such as GAS7, AQP10, HLF, and HOPX." (PMID 30867848, 2019). "Among them, GFI1B, HLF, and ZNF750 acted as protective factors of lung cancer prognosis." (PMID 34925645, 2021). "In contrast, the correlations between PER3, TEF, HLF and DBP are not altered in lung cancer." (PMID 39004631, 2024).
triple-negative breast carcinoma (8 papers, 2022 to 2025). An invasive breast carcinoma which is negative for expression of estrogen receptor (ER), progesterone receptor (PR), and human epidermal growth factor receptor 2 (HER2). "As a transcriptional activator, HLF has been validated as a tumor suppressor in triple-negative breast cancer and ovarian cancer." (PMID 39872516, 2024). "We have also shown that HLF regulates ferroptosis, development, and chemoresistance in triple-negative breast cancer by activating tumor macrophage crosstalk." (PMID 37709768, 2023). "HLF has been reported to play a role in regulating the development of triple-negative breast cancer by activating tumor cell macrophage crosstalk, which also affects chemotherapeutic resistance." (PMID 37735483, 2023). "HLF regulates ferroptosis, development and chemoresistance of triple-negative breast cancer by activating tumor cell-macrophage crosstalk." (PMID 37968615, 2023). "In triple negative breast cancer (TNBC), hepatic leukemia factor (HLF) was regulated by TGFB1 secreted by tumor-associated macrophages." (PMID 37091802, 2023).
glioma (6 papers, 2022 to 2025). A benign or malignant brain and spinal cord tumor that arises from glial cells (astrocytes, oligodendrocytes, ependymal cells). "HLF shows the opposite tendency: lower expression in higher-grade gliomas and higher expression in lower-grade gliomas." (PMID 37400829, 2023). "Dysregulation of HLF has also been observed in many cancer types, including liver cancer, breast cancer, intrahepatic cholangiocarcinoma, glioma, and lung adenocarcinoma." (PMID 37709768, 2023). "Furthermore, the HLF gene has been uncovered to have a crucial regulatory function in developing several malignancies, including lung, renal, glioma, liver, and breast." (PMID 38711550, 2024). "Conversely, HLF acts as a tumor suppressor in glioma and lung adenocarcinoma." (PMID 37709768, 2023). "Moreover, the aberrant expression of HLF was found to extensively participate in the various processes of tumorigenesis; HLF was found to be downregulated in glioma and may promote the proliferation, metastasis, and radiosensitivity of cancer cells." (PMID 35205284, 2022). "Hepatic leukemia factor (HLF) is considered as an oncogenic transcript factor, and its high expression correlates with favorable prognosis in many cancers such as glioma and non-small cell lung cancer." (PMID 35184747, 2022). "Besides, it has been unearthed that HLF-mediated downregulation of miR-132 leads to TTK overexpression, which contribute to proliferation, and metastasis in glioma cancerous cells." (PMID 38711550, 2024). "However, in gliomas and LUAD, HLF functions as a tumor suppressor." (PMID 40421217, 2025).
breast carcinoma (5 papers, 2013 to 2024). "In a breast cancer mouse model, orally administered hLF enhanced intestinal IFN-γ production, which was associated with expansion of NKT cells and CD8+ T cells, as well as increased systemic cytotoxicity of tumor-specific CD8+ T cells." (PMID 37111542, 2023). "They report a similar downregulation of PER1, PER2, CRY2, and HLF, in breast cancer samples while CLOCK, ARNTL(BMAL1), and BHLHE40 levels remained relatively unchanged." (PMID 38319971, 2024). "Concerning cancer cells, hLf was found to arrest cell growth, in G1 to S transition phase of the cell cycle, in a model of breast cancer, the MDA-MB-231 cells." (PMID 32183434, 2020). "Both hLF and bLF, when administered orally to mice with squamous cell carcinoma or basal-like breast cancer tumors, were found to enhance the effectiveness of conventional chemotherapy drugs, such as cisplatin and tamoxifen, and more effectively control the tumor growth." (PMID 37111542, 2023). "By injecting an adenovirus expressing the hLf cDNA into the tumor site in mice bearing EMT6 breast cancer, Wang and coworkers demonstrated that hLf could significantly reduce tumor growth." (PMID 32183434, 2020).
hepatocellular carcinoma (5 papers, 2021 to 2025). A malignant tumor that arises from hepatocytes. "Studies have shown that HLF overexpression enhances sorafenib resistance in hepatocellular carcinoma and promotes the proliferation and metastasis of triple‐negative breast cancer (TNBC) cells." (PMID 40236774, 2025). "On the contrary, HLF overexpression was found to promote the evolution of sorafenib resistance in patients with hepatocellular carcinomas via upregulation of OCT4 and SOX2." (PMID 35205284, 2022). "A study of hepatocellular carcinoma suggested that the role of HLF in inducing sorafenib resistance and in promoting tumor progression by activating c-Jun may help to discover new targets for cancer therapy." (PMID 34603375, 2021). "HLF transactivates c-Jun to promote tumor-initiating cell generation in hepatocellular carcinoma." (PMID 33428603, 2021).
cervical carcinoma (4 papers, 2014 to 2022). A carcinoma arising from either the exocervical squamous epithelium or the endocervical glandular epithelium. "This study also found that high expression of HLF was associated with a better prognosis of cervical cancer." (PMID 35184747, 2022). "Consistently, in a murine model of cervical carcinoma expressing hLf, Shi and Li demonstrated that the reduction of tumor growth in the hLf-treated group was associated to an induction of NK cells activity and an increase of CD4+ and CD8+ T lymphocytes in peripheral blood." (PMID 32183434, 2020). "The present study extended the observation to cervical cancer and demonstrated the effects of Ad-hLF on the immune response of U14 cervical carcinoma-bearing mice." (PMID 24520300, 2014). "The growth of cervical cancer is inhibited by Ad-hLF through the regulation of apoptotic factors." (PMID 24520300, 2014). "This study investigated the efficacy of hLF on the inhibition of U14 cervical cancer in vivo." (PMID 24520300, 2014). "Our results indicated that the inhibitory roles of Ad-hLF on cervical cancer may be related to its upregulation of the immune response against tumors." (PMID 24520300, 2014). "Due to the initiation of cytoimmunity against tumor cells by hLF, cervical cancer was suppressed." (PMID 24520300, 2014). "Although we determined that cervical cancer was inhibited through the cytoimmunity initiated by hLF, it remains unclear how to directly inhibit the tumor by hLF." (PMID 24520300, 2014). "After Ad-hLF was i.t. injected, VEGF expression in tumor tissue was significantly decreased, which suggests that Ad-hLF may directly downregulate VEGF so that the vascular components in the tumor are not formed, causing inhibition of cervical cancer." (PMID 24520300, 2014).
epilepsy (4 papers, 2020 to 2023). A brain disorder characterized by episodes of abnormally increased neuronal discharge resulting in transient episodes of sensory or motor neurological dysfunction, or psychic dysfunction. "First, circadian rhythm genes (BMAL1 and CLOCK), and their transcription factor complex, BMAL1–CLOCK, are known to influence the expression of other genes that are causally involved in epilepsy (for example, PAR DBP, TEF, and HLF)." (PMID 33192961, 2020).
non-small cell lung carcinoma (4 papers, 2021 to 2025). A group of at least three distinct histological types of lung cancer, including non-small cell squamous cell carcinoma, adenocarcinoma, and large cell carcinoma. "Downregulation of the circadian rhythm regulator HLF promotes multiple-organ distant metastases in non-small cell lung cancer through PPAR/NF-κB signaling." (PMID 34970597, 2021). "Aberrant expression of RAB25 promotes tumorigenesis of skin squamous cell carcinoma, while HLF down-regulation promotes distant metastases in non-small cell lung cancer." (PMID 34221975, 2021). "Additionally, previous studies have shown that HLF downregulation promotes multi-organ distant metastases in non-small cell lung cancer via NF-κB/p65 signaling." (PMID 40473600, 2025). "Intriguingly, this TCF3–HLF fusion protein has not been identified in solid cancers, and the role of HLF in solid tumors was not appreciated until recently, including carcinogenesis in liver, distant metastases in non-small cell lung cancer and cell stemness in ovarian cancer." (PMID 40473600, 2025).
ovarian carcinoma (4 papers, 2018 to 2025). A malignant neoplasm originating from the surface ovarian epithelium. "In ovarian tissue and ovarian stem cells, HLF expression is upregulated, promoting ovarian cancer stem cell properties, proliferation, as well as metastasis." (PMID 40421217, 2025). "Herein, we reported that HLF expression was upregulated in OC tissues and ovarian cancer stem cells (CSCs)." (PMID 37709768, 2023). "However, the role of HLF in the regulation of ovarian cancer (OC) remains unknown." (PMID 37709768, 2023).
prostate carcinoma (4 papers, 2012 to 2025). A carcinoma that arises from epithelial cells of the prostate gland. "Among these six, HLF, JUN, c-MYC, EGR1, SMAD1, and HIF1A, were also identified as PTEN-controlled TFs, and four, ESR2, MYB, RELA, and USF1, as prostate cancer-related TFs." (PMID 22347425, 2012).